APOE (apolipoprotein E)
Diseases named in the same sentence as APOE in open-access papers (continued):
Sharing a sentence is not in itself a finding about the gene and the disease.
atherosclerosis (continued). "To examine the role of lncRNA H19 and evaluate its treatment prospective in atherosclerosis, we overexpressed or knocked down lncRNA H19 in vivo using AAV in apoE−/− mice." (PMID 34820432, 2021). "In another mouse model of human cardiovascular disease, APOE*3-Leiden.CETP, resveratrol reduced atherosclerosis lesion and improved plaque stability as well comparable to cholesterol lowering drug atorvastatin in mice." (PMID 34771008, 2021). "It has been reported that overexpression of PCSK9 enhances the development of atherosclerosis and knockout of PCSK9 reduces the levels of aortic cholesterol in apoE−/− mice." (PMID 33767172, 2021). "Transgenic mice expressing both the human mutant apolipoprotein E form APOE*3-Leiden and human cholesteryl ester transfer protein (CETP), i.e. APOE*3-Leiden.CETP mice, feature a moderate hyperlipoproteinemia and atherosclerosis phenotype." (PMID 34052976, 2021). "ApoE−/- and LDL-R−/− mice are two models commonly used in atherosclerosis research that require hypercholesterolemia induction." (PMID 34975474, 2021). "Then, the aortic arch and abdominal aorta of ApoE−/− mice undergo NIR-II imaging were dissected, and the atherosclerotic plaque was observed, indicating the mice had remarkable atherosclerosis which was consistent with NIR-II imaging result." (PMID 34583680, 2021). "In this study, we created a new model of VSMCs specifically expressing sterol-resistant SCAP (D443N mutant) in both C57BL/6J and ApoE-/- mice to reveal the effects of SCAP on the NLRP3 inflammasome in VSMCs and the development of atherosclerosis." (PMID 34094640, 2021). "In addition, in APOE-deficient mice fed a high-fat-diet or normal chow for 16 weeks, levels of VEGF-A did not significantly differ between the two groups, whereas VEGF-C serum levels were significantly higher in high-fat-diet mice with advanced atherosclerosis and marked hypercholesterolemia." (PMID 33761122, 2021). "Experiments in ApoE −/− mice have shown that the increased methylation of the promoter region of ABCA1 decreases its expression and promotes atherosclerosis development." (PMID 34940525, 2021). "For detailed investigations, we used an in vitro human atherosclerosis MΦ model, and in vivo GDF-15−/−/ApoE−/− mice under CED, to study the role of GDF-15 on autophagic processes in atherosclerotic lesions." (PMID 34571994, 2021). "In this study, we used apoE−/− mice and ox-LDL induced THP-1 derived macrophages to explore the mechanisms of MCC950, a selective NLRP3 inhibitor in treating atherosclerosis." (PMID 34588488, 2021). "In fact, in ApoE−/− mice, LXA4 treatment blocks atherosclerosis progression in the aortic root and thoracic aorta." (PMID 33804219, 2021). "Development of atherosclerosis is retarded in PXR and apoE double knockout (PXR−/− and ApoE−/−) mice." (PMID 33401598, 2021). "APOE*3-Leiden.CETP mice with modest hyperlipidemia and atherosclerosis can develop atherothrombosis upon transient Proc-silencing." (PMID 34052976, 2021). "In this study, we used an ApoE−/- mouse model and in vitro cell lines, including RAW264.7 cells and BMDMs, to explore the mechanisms of DLTs in treating atherosclerosis." (PMID 34566648, 2021). "In mouse atherosclerosis, 43% of α-SMC-actin+ cells expressed CHIP in plaques of HFD-fed ApoE−/− mice versus 66% in chow-fed mice, and HFD-fed ApoE−/− mice showed reduced CHIP mRNA expression in their aortas versus chow-fed mice." (PMID 33353368, 2021). "Apolipoprotein E (ApoE)−/− mice fed a high cholesterol diet have high plasma concentrations of LDL-C and develop atherosclerosis." (PMID 34299217, 2021). "FXR protected mice against atherosclerosis by inhibiting the expression of CYP7A1 and CYP8B1 in ApoE−/− mice." (PMID 33401598, 2021). "In fact, in ApoE and FPR2 double-knock-out mice increased lesions size in early stages of atherosclerosis have been described." (PMID 33804219, 2021).
atherosclerosis (continued). "In contrast, transgenic mice expressing both human mutant APOE form APOE*3-Leiden and human cholesteryl ester transfer protein (CETP) i.e. APOE*3-Leiden.CETP mice, feature a moderate and easy modifiable hyperlipoproteinemia and atherosclerosis phenotype." (PMID 34052976, 2021). "In our study, we observed the increased level of serum TC, TG, and LDL-c in ApoE−/− mice exposed to CIH, accompanied by accelerated atherosclerosis." (PMID 34765657, 2021). "Nevertheless, although useful in assessing plaque composition, ApoE−/− mice do not seem to be susceptible to plaque rupture even on a high-fat diet over a year, limiting the employment of this animal model in studying pathophysiological complications that characterize atherosclerosis in humans." (PMID 34206655, 2021). "ApoE−/− mice injected with AOPPs plus rapamycin showed a decline in the expression of senescence associated protein p16 and a narrow in the aortic plaque area, which implied autophagy activation could attenuate AOPP-induced vascular senescence and might slow down the development of atherosclerosis." (PMID 35187108, 2021). "Moreover, TMAO may have a direct influence on cardiac oxidative stress, but it stimulated mitochondrial ROS generation and inhibited manganese superoxide dismutase 2 (SOD2) activation and sirtuin 3 (SIRT3) expressions in HUVECs and aortas in apolipoprotein E (ApoE)-KO mice with atherosclerosis." (PMID 34201938, 2021). "Similar to the observation in humans, the mRNA and protein levels of CILP2 in the aorta samples of ApoE KO mice were significantly higher than in those of control mice, further confirming that CILP2 is related to atherosclerosis." (PMID 33204392, 2020). "In this study, we used the apolipoprotein E (ApoE) model and angiotensin II- (Ang II-) induced VSMCs model to elucidate the pharmacological mechanism of ISL to inhibit atherosclerosis." (PMID 32328171, 2020). "It should be noted, however, that only female APOE*3‐Leiden.CETP mice develop hypercholesterolemia and atherosclerosis upon feeding a cholesterol‐rich diet." (PMID 31599473, 2020). "To investigate the role of the immunoproteasome subunit LMP10 in the development of atherosclerosis, we first examined the expression of LMP10 in the aorta of ApoE ko mice after 8 weeks of atherogenic diet (ATD) feeding." (PMID 33195259, 2020). "Furthermore, previous studies have reported that Stat1 deficiency instituted by using a bone marrow transplantation technique could not only suppress M1 polarization but also decrease foam cell formation in macrophages and reduce atherosclerosis in ApoE−/− mice." (PMID 31924749, 2020). "In this study, we found that THD exerts therapeutic effects on both atherosclerosis and AD in HFHC-fed ApoE-/- mice." (PMID 33121058, 2020). "In a progeria model of ApoE−/− mice, ER stress and the UPR were identified as drivers of VSMC death, which further accelerated atherosclerosis." (PMID 32963706, 2020). "For non-exposed controls (baseline), APOE4 vs APOE3 differed in 300 genes related to known APOE pathways including LXR/RXR, Atherosclerosis, and Rheumatoid arthritis." (PMID 32579111, 2020).
atherosclerosis (continued). "In the present study, in order to understand the role of BRCA2 in endothelial dysfunction and apoptosis in atherosclerosis, we measured the expression level of BRCA2 in the aorta of the high‐fat diet versus normal diet fed ApoE‐/‐ mice." (PMID 32638521, 2020). "ApoE is found abundantly in the lipid-rich deposits of AMD, DDD, atherosclerosis and Alzheimer’s disease patients." (PMID 33363547, 2020). "Since some of the observed alterations might be caused, at least in part, by the lack of apolipoprotein E, we sought to generate an alternative mouse model of progerin-dependent atherosclerosis development to validate and extend the findings in Apoe−/−LmnaG609G/G609G mice." (PMID 33049978, 2020). "We subjected APOE*3‐Leiden.CETP mice to weekly shifts in light‐dark cycle and observed a striking increase in atherosclerosis development." (PMID 31599473, 2020). "It has been proved that immunizing ApoE−/− mice with PC conjugate results in the increase of PC antibody and ox-LDL antibody and the decrease of atherosclerosis." (PMID 32002588, 2020). "In a previous study, we investigated the effects of Ron receptor signaling on macrophage polarization in the pathogenesis of atherosclerosis, as well as non-alcoholic steatohepatitis (NASH) using a high-fat high-cholesterol fed ApoE KO mouse model." (PMID 32796650, 2020). "In this study, we exposed female APOE*3-Leiden.CETP mice, a well-established model for human-like lipid metabolism and atherosclerosis, to either a regular light-dark cycle or to constant bright light for 14 weeks." (PMID 32915671, 2020). "Here, we explored the role of another subunit of LMP10 in the disease process, using ApoE knockout (ko) mice fed on an atherogenic diet (ATD) containing 0.5% cholesterol and 20% fat for 8 weeks as an in vivo atherosclerosis model." (PMID 33195259, 2020). "In vivo experiments confirmed that SalB reduces atherosclerosis in ApoE−/− mice and reduces inflammatory markers including IL-6, IL-1β, TNF-α, and oxLDL in the serum sample of ApoE−/− mice fed a high-fat diet." (PMID 33062143, 2020). "Moreover, apolipoprotein-E-deficient mice with FABP4 deficiency were found to be protected against atherosclerosis with or without induction by high-cholesterol Western diets, but how FABP4 deficiency can alter insulin resistance and lipid metabolism remain to be revealed." (PMID 33105856, 2020). "Conversely, a protective role for AT2R in atherosclerosis has been shown, as AT2R/apolipoprotein E (ApoE)–double-knockout (AT2R/ApoE-DKO) mice were shown to have increased plaque burden." (PMID 32630530, 2020). "The ApoE−/− model can also be useful for studying the smoking-exacerbated condition COPD, in addition to atherosclerosis, in tobacco and nicotine studies." (PMID 32331221, 2020). "In lesions of both ApoE-knockout mice and human coronary bypass grafts, endogenous TLR4 ligands are present, implicating a role for TLR expression in atherosclerosis." (PMID 32076951, 2020). "The APOE*3-Leiden transgenic mouse model is perhaps the most relevant model of impaired RLP removal and resulting increased atherosclerosis." (PMID 32849290, 2020). "In another study employing ApoE−/− mice, CRP promoted early changes of atherosclerosis by directly increasing the transcytosis of LDL across endothelial cells and increasing LDL retention in vascular walls." (PMID 31379851, 2019).
atherosclerosis (continued). "Apolipoprotein-E−/− and the low-density lipoprotein (LDL)−/− mice are important models for studying the pathogenesis of atherosclerosis." (PMID 31466329, 2019). "In ApoE−/− mice, disruption of TGF-β signaling enhances atherosclerosis, whereas TGF-β overexpression reduces atherosclerotic lesion vulnerability and atherosclerosis." (PMID 31653058, 2019). "In this study, we demonstrated that CUMS significantly increased atherosclerosis lesions as well as HMGB1 levels both in serum and aortas of ApoE-/- mice." (PMID 30881312, 2019). "To study the function of MIAT and examine the therapeutic potential in atherosclerosis, we knocked-down MIAT in vivo using systemically delivered viral MIAT shRNA in ApoE−/− mice." (PMID 30755588, 2019). "CD248 was shown to promote atherosclerosis as ApoE and CD248 double KO mice displayed less atherosclerosis when fed a Western style diet." (PMID 31287944, 2019). "In order to investigate the impact of MVP on atherosclerosis, we generated the MVP and ApoE double knockout (MVPKOApoEKO) mice." (PMID 30996248, 2019). "As expected, atherosclerotic plaques in both the branchiocephalic arteries and aortic sinus were dominantly increased in ApoE−/− mice in the AS group after 24‐week high‐fat diet treatment, while RSV treatment inhibited the progression of atherosclerosis." (PMID 30957417, 2019). "The Atherosclerosis-prone, C57BL/6 J ApoE−/− mice model is characterized by a poor liver lipoprotein clearance of diet-derived chylomicrons and liver-derived VLDL remnants with accumulation of cholesterol ester-enriched particles in blood." (PMID 31889910, 2019). "While there has yet to be consensus on the effect of CLA on atherosclerosis, the majority of CLA supplementation studies in apoE−/− mice show a suppression or regression of atherosclerosis." (PMID 30754681, 2019). "PCSK9 inhibition decreased total cholesterol in serum of APOE*3Leiden.CETP mice and prevented the development of atherosclerosis." (PMID 31366894, 2019). "Moreover, AGE treatment inhibited inflammatory response to prevent atherosclerosis by reducing the serum level of C-reactive protein and thromboxane B-2, the protein level of TNF-α and IL-1 receptor-associated kinase 4, and increasing AMPK activity in the liver of apolipoprotein E-knockout mice." (PMID 31284512, 2019). "Genetic ablation of iNOS in ApoE KO mice reduces low-density lipoprotein (LDL) oxidation and advanced atherosclerotic lesions, suggesting iNOS is key in the development of atherosclerosis." (PMID 31382355, 2019). "In a genetic mouse model of atherosclerosis, the PVAT from a apolipoprotein E-null (ApoE−/−) mouse promoted atherosclerotic plaques in a region where it does not usually form in ApoE−/− mice." (PMID 32133436, 2019). "FGF21 suppressed the development of atherosclerosis, and the administration of FGF21 ameliorated Fas-mediated apoptosis in apoE−/− mice." (PMID 30157856, 2018). "In order to explore the role of SMC-MR in atherosclerosis, a well validated inducible SMC-specific MR knockout mouse was crossed to the atheroprone ApoE−/− background." (PMID 30038907, 2018).
atherosclerosis (continued). "Atherosclerosis is a chronic inflammatory disease and to evaluate the expression of GPR84 in this condition, ApoE−/− mice were fed a HFD for 6 and 12 weeks, then sacrificed and tissues collected." (PMID 29973940, 2018). "The expression of LOX-1 in the aortic root was dramatically (P<0.001) attenuated by LHRD treatment (400 mg/kg/d) compared with vehicle treatment control in ApoE−/− mice, indicating that LHRD ameliorates atherosclerosis through downregulation of LOX-1." (PMID 30402125, 2018). "Through the in vivo test, ApoE KO mice fed a high-fat diet and C57BL/6 wild-type mice fed a normal diet for four weeks made up the atherosclerosis model and control group, respectively." (PMID 29795012, 2018). "We have generated a novel mouse model of endothelial cell and leucocyte-targeted Gch1 deletion, crossed with the hyperlipidemic ApoE–/– mouse, to test the cellular requirement for BH4 in the pathology of atherosclerosis." (PMID 29596571, 2018). "The studies constitute a reference for our research carried out on a standard experimental model of atherosclerosis, i.e., C57BL6 ApoE-knockout mice." (PMID 29614743, 2018). "In this subject, reduction of LOX-1 expression in aortic plaques lesions of ApoE−/− mice treated by LHRD is obviously significant, suggesting that LHRD attenuates atherosclerosis through downregulation of LOX-1." (PMID 30402125, 2018). "In ApoE−/− mice fed an HFD, star anise improved the lipid profiles, and ameliorated atherosclerosis." (PMID 30423840, 2018). "The expression of those proteins, as well as the presence of apoptotic cells, was analyzed by immunohistochemistry in experimental atherosclerosis using BATIRKO; ApoE−/− mice, a model showing more aggravated vascular damage than ApoE−/− mice." (PMID 29463262, 2018). "Our results indicated that p-EGFR were increased in all three cell types (macrophages, SMCs, and ECs), which contribute mainly to atherosclerosis, in HFD-fed ApoE−/− mice." (PMID 28374780, 2017). "The authors showed that the osteoblast number and function were dramatically reduced in trabecular and cortical bone of the ApoE-knockout, high-fat-diet-fed (HFD) mice, a mouse model of atherosclerosis." (PMID 28194536, 2017). "The severity of atherosclerosis in MMP-2 and ApoE double gene knockout mice has been reported to be less than that in ApoE single gene knockout mice." (PMID 28450836, 2017). "ApoE knockout mice with mitoNEET overexpression in PVAT showed significant downregulation of inflammatory genes and showed reduced atherosclerosis development upon high fat diet feeding when kept in a 16°C environment." (PMID 29311966, 2017). "We found significant anti‐atherosclerotic properties in ApoE‐/‐ mice and extended these observations to show that AVE0991 affects atherosclerosis development at early stages of plaque formation, in the descending aorta in young ApoE‐/‐ mice." (PMID 27935022, 2017). "Furthermore, whole genome hypomethylation was present in peripheral blood mononuclear cells and aortas of 4-week-old ApoE-null mice, preceding any histological sign of atherosclerosis, which means that DNA methylation maybe a potential biomarker for early atherosclerosis in diabetic patients." (PMID 28183874, 2017).